HMGB1 (high mobility group box 1)
Diseases named in the same sentence as HMGB1 in open-access papers (continued):
Sharing a sentence is not in itself a finding about the gene and the disease.
tumor (continued). "However, in GC, knockdown of TP73-AS1 effectively suppresses GC cell proliferation and induces apoptosis by targeting the HMGB1/RAGE pathway, while also significantly increasing tumor cell sensitivity to cisplatin chemotherapy." (PMID 40332793, 2025). "Importantly, serum HMGB1 levels were markedly higher in UBC patients and showed a positive correlation with tumor stage and tissue expression, underscoring its potential as a circulating DAMP capable of reflecting the tumor’s inflammatory and metabolic state." (PMID 41009692, 2025). "While HMGB1 acts as a kind of DAMPs to promote the activation and maturation of DCs, thereby enhancing the antitumor immunity of CD8+T cells, it can also function as a tumor-promoting factor, leading to immunosuppression." (PMID 40169575, 2025). "To investigate the impact of HMGB1 on CRC cell function in vivo, we conducted a nude mouse tumorigenesis assay to determine whether the decreased expression of HMGB1 inhibited tumor growth in vivo." (PMID 40975711, 2025). "Extracellular HMGB1 promotes the release of cytokines, such as IL-6 and IL-8, through activation of the MAPK- and MyD88-dependent NF-κB pathways, which stimulates the proliferation, angiogenesis, EMT, invasion, and metastasis of tumor cells." (PMID 41296391, 2025). "Subsequent immunohistochemical analyses using Ki-67 and cleaved caspase-3, as well as Hmgb1 markers to probe tumor proliferation, apoptosis, and necrosis, yielded no notable disparities between the two mouse cohorts." (PMID 41330921, 2025). "Furthermore, cytoplasmic HMGB1-mediated STAT3 phosphorylation induced STAT3 target genes, including EMT phenotypes as well as PD-L1 expression, and contributed to tumor progression in mice." (PMID 40389855, 2025). "In the process of cell death, tumor cells will release DAMPs, such as CRT and HMGB1." (PMID 40535125, 2025). "In the PAN02 pancreatic cancer model, HMC nanoparticles facilitate tumor cell internalization, triggering robust ROS bursts that promote apoptosis and ICD, evidenced by elevated calreticulin (CRT) exposure, ATP secretion, and reduced nuclear HMGB1 retention." (PMID 41451226, 2025). "Furthermore, we confirmed that either HMGB1 knockdown in tumor cells or the use of TAK-242 can inhibit this process, underscoring the critical roles of HMGB1 and the TLR4 receptor in the M1 polarization of macrophages." (PMID 40082916, 2025). "In HCC, ferroptosis does not provide cell-autonomous tumor suppression but triggers tumor infiltration of MDSCs via HMGB1, thereby eliciting an adaptive immune response." (PMID 38609997, 2024). "Up to now, no literature has explored the direct regulatory relationship between HMGB1 and IDO in tumor tissues, and only previous studies have suggested that there may be a related regulatory mechanism between them." (PMID 39314628, 2024). "Although the inflammatory response induced by HMGB1 is helpful in tumor immunotherapy, its inflammatory side effects should not be underestimated." (PMID 38725632, 2024). "Upon internalization by tumor cells, CuX-P induced cuproptosis through the liberation of DSF/Cu2+, while also triggering elevated CRT expression and HMGB1 release, thereby facilitating the recognition and activation of tumor-associated antigens by dendritic cells." (PMID 39691393, 2024). "The researchers did not correlate tumour HMGB1 expression with serum or explore relationship between tumour expression and clinicopathologic or outcome data." (PMID 38353760, 2024). "Erastin aggravated the hyper oxidation of tumor cells, induced the ferroptosis to suppress the proliferative signals, and triggered innate and adaptive immune responses by releasing immunogenic molecules including CRT and HMGB1." (PMID 38902759, 2024). "Our previous study revealed that hypoxia could promote the release of HMGB1 from HCC cells, which interacts with mitochondria to promote tumor progression." (PMID 38378644, 2024).
tumor (continued). "This HMGB1-induced activation leads to the appearance in PBMC of non-canonical cytotoxic T-lymphocytes capable of lysing HLA-negative tumor cells." (PMID 38203798, 2024). "Given that CRT, HMGB1, and ATP are established biomarkers of ICD, our findings suggest a potential synergistic effect of PEG-MnMOF and PTX in promoting optimal ICD induction in tumor cells." (PMID 38715912, 2024). "However, other genes regulation involved in anti-tumor immune response and resistance to immunotherapies, NECTIN4, HMGB1, TNFSF18, by CaPa or CaGe seem to be dependent on the cell line used and thus to be more heterogeneous." (PMID 38581044, 2024). "TrxR inhibition might additionally promote oxidation of HMGB1, and the subsequent inhibition of the CXCL12/HMGB1 heterocomplex formation in the tumor microenvironment." (PMID 38803493, 2024). "HMGB1 plays a key role in the development of various tumors by regulating the PI3K/AKT/NF-κB/VEGF/EMT and AMPK/mTOR signaling pathways, and it can act as both a tumor suppressor and an oncogenic factor." (PMID 37897664, 2024). "Notably, elevated secretion of high mobility group box 1 (HMGB1) and adenosine triphosphate (ATP) after IASNDS treatment signified the occurrence of ICD within tumor cells." (PMID 38762500, 2024). "Furthermore, treatment with RSL3 for 1 h induced a notable release of HMGB1 and ATP from ferroptotic MCA205 and GL261 cells, which facilitated the maturation of dendritic cells and suppressed tumor growth in a vaccine tumor mouse model." (PMID 38844964, 2024). "Additionally, research efforts should investigate the interplay between the HMGB1/RAGE axis and other signaling pathways for a more comprehensive understanding of the regulatory network governing autophagy in tumor cells." (PMID 38529373, 2024). "Based on the potential association between HMGB1 and IDO, dual-target combination therapy with HMGB1 and IDO inhibitors may have better efficacy than tumor immunotherapy by inhibiting the activity of HMGB1 or IDO alone in the future." (PMID 39314628, 2024). "Moreover, the secretion of high-mobility group box 1 (HMGB1) and calreticulin (CALR) from tumor cells induced TAMs’ M1-type polarization, dendritic cell (DC) maturation, and CD8-positive T-cell activation, resulting in a prolonged and enhanced immune response." (PMID 39457052, 2024). "Of note, in CD3+ T cells, but not in the tumor cell lines, the cysteine in position 106 was either in the reduced or oxidized isoform, suggesting the presence of both HMGB1 monomers and dimers in these cells." (PMID 38803493, 2024). "For example, High Mobility Group Box 1 (HMGB1), belonging to the HMGB superfamily, is a DNA-binding protein that regulates various cellular processes such as inflammation, cell differentiation, and tumor cell migration." (PMID 39179991, 2024). "Collectively, these results indicate that MSI2 improves tumor immunity in CRC and that better patient outcomes may be due to HMGB1-mediated immune infiltration." (PMID 38347600, 2024). "Thereafter, HMGB1 can act as a cytokine or chemokine, binding to cell surface receptors, such as TLRs and RAGE, prompting immune cells to secrete various inflammatory cytokines, creating a microenvironment in favor of tumor initiation and progression." (PMID 37897664, 2024). "The production of ROS not only facilitates the direct eradication of tumor cells but also enhances the release of antigens, including calreticulin (CRT), heat shock proteins (HSPs), adenosine triphosphate (ATP), and high-mobility group box 1 (HMGB1)." (PMID 38607182, 2024). "However, the acetylation of these proteins has been confirmed to play a role in the regulation of tumor development, including SDHA, IDH1, and HMGB1." (PMID 38831454, 2024).
tumor (continued). "Heavy ion may boost the production of ATP, HMGB1, CRT, and other DAMPs more than typical ray, which results in stronger tumor cell ICD, according to both cell and animal research." (PMID 38495488, 2024). "The release of HMGB1 from dying cells during ICD, a distinct type of cell demise, not only represents the demise of the cell but also elicits an anti-tumor immune response that assists in eradicating tumor cells." (PMID 38529373, 2024). "Importantly, treatment with aAGd-NWs+RT also significantly promoted HMGB1 release and ATP secretion from the treated CT26 tumor cells, which can recruit and activate APCs." (PMID 38724527, 2024). "Notably, small molecules, such as miRNA-218, ethyl pyruvate (EP), and glycyrrhizin exhibit the ability to inhibit the HMGB1/RAGE axis, restraining tumor development." (PMID 38529373, 2024). "High mobility group box-1 protein (HMGB1) is a non-histone chromosomal protein involved in the regulation of tumor autophagy and apoptosis." (PMID 38785969, 2024). "Autophagy regulated by HMGB1 has both positive and negative effects as it can promote tumor cell proliferation as well as induce tumor cell death." (PMID 37897664, 2024). "Such immunogenic features of irradiation-driven cell death are bolstered by several pivotal factors including the release of High-Mobility Group Protein B1 (HMGB1), the emission of adenosine-triphosphate (ATP), and the exposure of Calreticulin (CRT) on the tumor cell surface 37-42." (PMID 38323315, 2024). "In addition, the combined treatment of Fn-OMV and oHSV significantly increased the release of nuclear high mobility group box 1 (HMGB1) and tumor necrosis factor-alpha (TNF-α) in tumor cells compared to oHSV treatment alone." (PMID 38693119, 2024). "The increased expression and release of major nucleus-derived DAMPs, including HMGB1 and HSP90, can augment the local inflammatory response, thereby promoting the infiltration of macrophages into the tumor’s periphery and their polarization to the M1 phenotype." (PMID 38565963, 2024). "Compared to tumor cell death mediated by chemotherapy or mechanical damage, apoptosis induced by RIG-I triggers caspase-3-mediated immunogenic cell death, characterized by the release of HMGB1 and translocation of calreticulin to the outer cell membrane." (PMID 38523155, 2024). "Although the comprehensive molecular mechanisms underlying TLC388-inducd antitumor immunity remain undetermined, we proposed that TLC388 promotes DC maturation by enhancing tumor antigen presentation through STING signaling and inducing immunogenic cell death such as HMGB1, ANXA1 and CRT." (PMID 38564022, 2024). "Thus, we confirmed that HMGB1 is a TREM-1 ligand and showed that it can activate cytotoxic lymphocytes that kill tumor cells that evade immune control." (PMID 38203798, 2024). "They found that patients with favorable prognostic factors (tumor size <2 cm, N+ <3, positive HR status, tumor grade < III) had a low risk of metastatic relapse, regardless of LC3B and HMGB1 expression." (PMID 39830522, 2024). "When HMGB1 is released from dying cells, the activated TLR4/MyD88 pathway enhances INF-β signal transduction, stimulates immune activity, and up-regulates the expression of PD-L1 in neighboring surviving tumor cells." (PMID 38785969, 2024). "Overall, the relationship between the HMGB1/RAGE axis and tumor cell apoptosis provides new ideas and potential targets for tumor treatment, but further research is needed to deepen our understanding of its mechanisms and develop more effective treatment strategies." (PMID 38529373, 2024). "The noncoding regulatory role of HMGB1 in HCC upregulates PD‐L1+ exosomes, which reduces apoptotic cells’ frequency and leads to tumor progression, and may explain treatment resistance and predict immunotherapy." (PMID 38807975, 2024).
tumor (continued). "Because of the absence of ROS, dying tumor cells were able to provide antigens and nonoxidized HMGB1 to prime and promote the function of T cells for effective anticancer therapy." (PMID 38748805, 2024). "In addition, knockdown of HMGB1 and FOXO1 simultaneously restored the changes in the tumor size, volume and fluorescence intensity in mice induced by circHERC1 overexpression." (PMID 37932766, 2023). "In addition, WEE1 inhibitors significantly increased the expression of CRT, HMGB1, and other DAMPs in TME, which are closely associated with immunogenic cell death (ICD), suggesting that WEE1 inhibitors may further enhance the efficacy of immunotherapy and induce tumor cell death through ICD." (PMID 37305685, 2023). "For instance, ferroptotic PDAC cells can release KRAS-G12D protein, which drives tumor growth through polarization of macrophages, whereas the release of high mobility group box protein B1 (HMGB1) and membrane proteoglycan decorin (DCN) can stimulate anti-tumor cytotoxic T cell responses." (PMID 37601110, 2023). "HMGB1 upregulated tumor growth by 110.7 ± 8.2, 133.4 ± 1.3 and 140.7 ± 5.2% on days 1, 2 and 3, respectively, compared to controls not treated with HMGB1." (PMID 37210579, 2023). "Further in vivo and in vitro experiments found that Ir-pbt-Bpa can increase the level of intracellular HMGB1/ATP, CD8+ T cells, and memory T cells, as well as reduce regulatory T cells in tumor-bearing mice, resulting in strong and long-lasting antitumor immunity." (PMID 37894410, 2023). "Interestingly, irrespective of how we pulled out the complex from Eto-CM, via fishing Hsp70 with specific antibodies or HMGB1 using HBHP-binding peptide, the result was the same: a reduction in A549 tumor cell repopulation." (PMID 37880798, 2023). "However, the release of various DAMPs, including ATP, HMGB1 and IL-1α, from dead tumor cells activates the NLRP3 inflammasome in DCs, which can lead to resistance to chemotherapy and promote tumor growth." (PMID 37497237, 2023). "Besides, although a positive correlation between HMGB1 expression and CD4+ memory T cells (R = 0.195, P ˂ 0.01) was observed, the correlation coefficient of other tumor-infiltrating immune cells was insignificant." (PMID 36907982, 2023). "In addition, even though tumor-derived HMGB1 is critical for SDT-related immunogenicity, researchers found that HMGB1 is also involved in tumor progression." (PMID 37168380, 2023). "In accordance with the spreading of XVir-N-31 in the LN-229 GBMs after the INA of LX-2/XVir, HMGB1 was clearly evident within the tumor area 12 days after the INA of LX-2/XVir, but not if unloaded shuttle cells were intranasally applied." (PMID 37894279, 2023). "Taken together, these data demonstrated that the tumor‐derived HMGB1‐gDNA complex engaged in activation of the cGAS‐STING‐type I IFNs and NF‐κB pathways that further primed the inflammasome, which was finally activated by the tumor‐derived oxLDL in DCs." (PMID 37786300, 2023). "HMGB1, a substance generated by dying tumor cells, interacts with TLR4, a receptor crucial for both innate and adaptive immune responses, to initiate the processing of tumor antigens by mature DCs and the anticancer immune response." (PMID 37752941, 2023). "Indeed, in the mice that received XVir-N-31 intratumorally, HMGB1, HSP70 and YB-1 were evident in the core tumor for a long time post-treatment." (PMID 37894279, 2023). "Moreover, Gly also contributes to regulating the tumour microenvironment by directly binding and blocking HMGB1 (high-mobility group box-1), an immunosuppressive cytokine that helps transformed cells evade the immune system." (PMID 38138866, 2023). "As tumor cells undergo ICD, the dying cells also release high-mobility group box protein 1 (HMGB1)." (PMID 37626741, 2023).
tumor (continued). "HMGB1 was discovered to bind the Receptor of Advanced Glycation Endproducts (RAGE) receptor on glioma cells in vitro, resulting in the activation of NF-κB and subsequent upregulation of IL-8 expression, thereby promoting tumor progression in breast cancer." (PMID 36942262, 2023). "HMGB1 released from irradiated breast cancer cells stimulated M1-type macrophages to secrete high levels of TNF-α and low levels of IL-10, facilitating drastic anti-tumor activity." (PMID 37833255, 2023). "Tumor cells undergoing ICD provoke immunostimulatory effects owing to the exposure or release of DAMPs, such as heat shock proteins (HSPs), calreticulin (CRT), the high-mobility group box 1 (HMGB1) protein, and adenosine triphosphate (ATP)." (PMID 38017537, 2023). "It seems reasonable, but not yet proven, that CXCL12•HMGB1 complexes influence tumor cell migration and metastasis." (PMID 37446102, 2023). "Impairment of the HMGB1-RAGE signaling axis by OVesRAGE, an oHSV designed to secrete endogenous secretory RAGE (esRAGE), inhibits MEK-Erk signaling and endothelial cell activation, resulting in enhanced anti-tumor efficacy." (PMID 36789106, 2023). "Extracellularly released high mobility group box 1 (HMGB1) and ATP engage and activate antigen-presenting cells, contributing to the infiltration of tumor-specific T cells, while calmodulin calreticulin (CRT) exposed on the surface of dead cells provides an ‘eat me’ signal." (PMID 37215130, 2023). "HMGB1, while being dependent on Toll-like receptor 4 (TLR4), also improves antigen cross-presentation by DCs, hence leading to an adaptive immune response against the tumor." (PMID 37857049, 2023). "Therefore, HMGB1 is often released during ferroptosis and participates in the regulation of CD8+ T cells as tumor antigens." (PMID 38288118, 2023). "Furthermore, the expression of representative biomarkers of ICD (HMGB1 and CRT) within tumor sections was studied by immunofluorescence staining." (PMID 37221237, 2023). "Furthermore, Huang (2018) found that improvement in clinical outcome is resultant of cytosolic HMGB1 triggering dendritic cell maturation through TLR4 activation, whereby consequently recruiting PD-1+ tumor-infiltrating lymphocytes to the tumor site." (PMID 35841426, 2023). "Consequently, extracellular HMGB1 along with JQ1-induced release of calreticulin (CALR), and ATP will provoke immunogenic apoptosis of tumor cells." (PMID 37511951, 2023). "One limitation of our study is that we do not have information on the protein levels of the S100s and HMGB1 in the eight cell lines and in the tumor array." (PMID 37627239, 2023). "It is worth noting that NCTD alone did not induce tumor cell ICD while NCTD+OXA significantly increased ATP secretion, enhanced the amounts of membrane‐associated CRT, and dimmed the HMGB1 staining more efficiently than OXA alone." (PMID 37551065, 2023). "Of note, HMG family proteins such as HMGB1, HMGB2 and HMGB3 are elevated in human tumor cell NEPs in contrast to S100a4 in mice suggesting that NEP signaling through the RAGE pathway may be conserved between mice and humans." (PMID 36973439, 2023). "Furthermore, HMGB1 secreted by irradiated cancer cells stimulates macrophages to produce TNF-α via the TLR-4 signaling pathway, inhibiting tumor progression and metastasis." (PMID 38066523, 2023). "Interestingly, CX-4945 treatment lowered HMGB1, β-catenin, C-MYC, phosphor-MAX, IL-6, and CSNK2A1 protein levels in tumor tissues in CX-4945 treatment as compared with a vehicle." (PMID 37347224, 2023). "Given that PTT could induce ICD in tumor cells, we further explored whether ICG‐locking gel‐mediated PTT could exert an effect on CRT, ATP, and HMGB1." (PMID 38023716, 2023). "HMGB1 can activate TLR2 and TLR4 on dendritic cells (DCs) to initiate antigen presentation and cytokine secretion, activating antigen‐specific CD4+ T cells and CD8+ T cells to recognize and eradicate tumor cells." (PMID 37945630, 2023).